SNORD104 (small nucleolar RNA, C/D box 104)
Synonyms: U104
Gene: Small nucleolar RNA gene on chromosome 17 (64,146,083 to 64,146,152, forward strand). Ensembl gene ENSG00000199753.
Gene Ontology:
Biological process: RNA processing
Cellular component: nucleolus
Homologues: Orthologues: chimpanzee SNORD104 (100% identical), macaque SNORD104 (99% identical), guinea pig SNORD104 (96% identical), pig SNORD104 (94% identical), rabbit SNORD104 (94% identical), dog SNORD104 (90% identical), rat Snord104 (84% identical), mouse Snord104 (80% identical).
Diseases named in the same sentence as SNORD104 in open-access papers:
SNORD104 is named in the same sentence as 4 diseases in open-access papers, as found by Europe PMC text mining. Sharing a sentence is not in itself a finding about the gene and the disease. The quoted sentences say what the papers report.
endometrial cancer (1 paper, 2023). Primary or metastatic malignant neoplasm involving the endometrium (mucous membrane that lines the endometrial cavity). "Interestingly, in a recent report, the overexpression of SNORD104 was shown to promote endometrial cancer growth in preclinical models in vivo and in vitro." (PMID 37627150, 2023).
bacterial infections (1 paper, 2019). "However, snoRNA regulation has thus far hardly been explored in bacterial infections; together with the current study, SNORD104 dysregulation has been described previously in an investigation of another important mycobacterial infection." (PMID 31796535, 2019).
SNORD104 also shares sentences with these, for which no sentence is quoted: breast carcinoma (2 papers); leukemia (1).